ERCC8 (ERCC excision repair 8, CSA ubiquitin ligase complex subunit)
Diseases named in the same sentence as ERCC8 in open-access papers (continued):
Sharing a sentence is not in itself a finding about the gene and the disease.
Atrophy (1 paper, 2013). Any weakening or degeneration, especially through lack of use. "Overlap brain sites between the ERCC8 gene expression of Donor H0351.1016 from the Allen Brainmap and CS patient atrophy." (PMID 24324434, 2013).
Cachexia (1 paper, 2020). Severe weight loss, wasting of muscle, loss of appetite, and general debility related to a chronic disease. "Loss of transcription-coupled repair, which occurs with mutations in twofold excision repair of cross-complementing genes (ERCC6 and ERCC8) results in CS, which is characterized by progressive cachexia, severe growth retardation and leukoencephalopathy." (PMID 31752481, 2020).
cerebellar ataxia (1 paper, 2022). A neurological syndrome characterized by clumsy and uncoordinated movement of the limbs, trunk, and cranial muscles. "The mutant ERCC8 gene has recently been reported as a cause of ARCA as a missense mutation p.Gly257Arg has been linked to unique cerebellar ataxia in a Chinese family." (PMID 36231052, 2022). "In this study, we identified a novel homozygous missense mutation ERCC8:c176T>C (p.M59T) segregating with cerebellar ataxia in a consanguineous Pakistani family." (PMID 36231052, 2022). "Missense mutations in ERCC8 have been reported to cause milder phenotypes than protein truncating mutations, and ataxia can be part of a broad syndromic constellation of phenotypes or can appear as an isolated clinical feature." (PMID 36231052, 2022).
chronic atrophic gastritis (1 paper, 2017). Atrophic gastritis that is persistent and long-standing. "We also performed protein level analysis to compare ERCC6 and ERCC8 expression (alone or in combination) in chronic superficial gastritis (CSG), chronic atrophic gastritis (CAG) and GC, and to correlate SNPs jointly with gene expression." (PMID 28562347, 2017).
clear cell carcinoma (1 paper, 2021).
DNA repair disorder (1 paper, 2023). "The DNA repair disorder of CS is caused by ERCC6 or ERCC8 with a proportion around 1:2." (PMID 37592445, 2023).
gastric diseases (1 paper, 2017). "Besides, protein level analysis were performed to compare ERCC6 and ERCC8 expression in different stages of gastric diseases, and to correlate SNPs jointly with gene expression." (PMID 28562347, 2017). "Therefore, we supposed that ERCC6-ERCC8 joint expression was more suitable for discriminating normal and diseased mucosa, and ERCC8 was a better marker to distinguish CAG from other gastric diseases." (PMID 28562347, 2017). "Furthermore, individual and joint expression of ERCC6 and ERCC8 were also evaluated by immunohistochemistry in different gastric diseases, which have never been reported before." (PMID 28562347, 2017).
Huntington disease (1 paper, 2021). Huntington disease (HD) is a rare neurodegenerative disorder of the central nervous system characterized by unwanted choreatic movements, behavioral and psychiatric disturbances and dementia. "KEGG pathway analysis results further revealed that ERCC6 also functioned in Huntington’s disease and ERCC8 showed significant impacts in ubiquitin mediated proteolysis." (PMID 34316408, 2021).
lymph node metastasis (1 paper, 2021). "Expression of ERCC8 was statistically higher in patients with TNM stage I-II in comparison to stage III-IV (P < 0.001) (P < 0.001 for T stage; P = 0.002 for lymph node metastasis), and was higher in those with early-stage and small size (P = 0.031 and 0.007, respectively)." (PMID 34316408, 2021).
osteosarcoma (1 paper, 2025). A usually aggressive malignant bone-forming mesenchymal neoplasm, predominantly affecting adolescents and young adults. "Notably, ERCC8 and XPA have been previously implicated in DDP resistance, and we also demonstrated that they regulated the sensitivity of osteosarcoma cells to DDP treatment." (PMID 40019400, 2025).
Parkinson disease (1 paper, 2024). A progressive degenerative disorder of the central nervous system characterized by loss of dopamine producing neurons in the substantia nigra and the presence of Lewy bodies in the substantia nigra and locus coeruleus. "ERCC8 has also been identified as a comorbid factor in shared genetics between Parkinson disease and ALS." (PMID 38872308, 2024).
retinal degeneration (1 paper, 2022). Degeneration of the retina. "Importantly, those regions contained breed-specific genetic markers and candidate genes that are functionally related with pigmentation (e.g. PDE4D), UV protection (e.g. ERCC8), or retinal degeneration (e.g. CWC27, and CLUAP1)." (PMID 36288367, 2022).
T-cell lymphoma (1 paper, 2016). "Similarly, inhibition of Pim kinase in T-cell lymphoma cells downregulated genes involved in DNA repair, including XRCC2 (HR), XRCC5 (encoding Ku80, in the NHEJ pathway), and ERCC8 (nucleotide excision repair)." (PMID 27374090, 2016).
cancer (13 papers, 2010 to 2025). A tumor composed of atypical neoplastic, often pleomorphic cells that invade other tissues. "Excision repair cross-complementing group 6 and 8 (ERCC6 and ERCC8) have been implicated in ailments such as genetic diseases and cancers." (PMID 34316408, 2021). "Further support for this gene as a potential TSG is provided by the increased frequency of cancer in Cackayne's syndrome patients in which the ERCC8 gene is mutated." (PMID 20462409, 2010). "In brief, we hypothesized that downregulation of ERCC6 and ERCC8 may result in lower DNA repair capacity, thus elevating cancer susceptibility by allowing unrepaired DNA damage to remain, ultimately leading to carcinogenesis." (PMID 28562347, 2017). "We suggested that ERCC6 and ERCC8 downregulation could induce persistent existence of unrepaired DNA lesions, decreased DNA repair capacity and increased cancer susceptibility, and eventually lead to cancer progression." (PMID 34316408, 2021). "In contrast, it was observed that ERCC8 exhibited a positive correlation with resistance to cancer immunotherapy (specifically, anti-PD-1/PD-L1) in the datasets GSE111636 and GSE67501." (PMID 39192988, 2024). "Initially, we conducted an examination of mRNA expression levels of seven ERCC genes (ERCC1-6 and ERCC8) in various cancer tissues." (PMID 39192988, 2024). "Results of these experiments showed that the expression of ERCC6 and ERCC8 had clinical significance in ailments such as genetic diseases and cancers." (PMID 34316408, 2021). "However, it is unclear whether there are interactions among ERCC6 and ERCC8 SNPs, by which it may enhance the risk warning for GC or its precancerous diseases because SNP-SNP interactions could be more valuable than a single SNP in cancer prediction." (PMID 28562347, 2017). "Furthermore, we investigated the impact of ERCC family genes on PFI and observed that only ERCC6L and ERCC8 maintained a significant correlation with expression levels, indicating their potent influence on cancer-related mortality." (PMID 39582530, 2024). "MIR1.1HG and LOH12CR2 were expressed at higher levels in normal tissues than in cancer tissues, while the expression levels of ERCC8.AS1 and LINC00520 in tumor tissues were significantly higher than those in paired adjacent normal tissues, which showed similar expression trends to TCGA datasets." (PMID 36438557, 2022). "They found that urinary glyphosate level was associated with the methylation level of 24 CpG sites in the promoters of genes including some related to cancer, such as SF3B2, MSH4, and ERCC8." (PMID 39200696, 2024). "Several studies have reported a relationship between ERCC8/ERCC6 and the pathogenesis of CS; however, the prognosis ability or mRNA expression of ERCC8 in cancer is seldom reported." (PMID 30417012, 2018). "Cancer cells lacking ERCC6 or ERCC8 protein, which are responsible for DNA repair, may exhibit a more malignant and poorly differentiated phenotype." (PMID 34316408, 2021).
tumor (5 papers, 2017 to 2024). "AC010999.2, ERCC8 − AS1, and AC104971.3 were highly expressed in the low-risk subgroup, indicating their tumor-protective role." (PMID 39143529, 2024). "Surprisingly, an increase in ERCC GSVA scores displayed a positive tendency toward the activation of the cell apoptosis pathway, which is contradictory to experimental evidence that inhibition of ERCC1, ERCC6L, or ERCC8 promotes apoptosis of tumor cells." (PMID 39582530, 2024). "In addition, We evaluated the anti-tumor effects of ERCC8 in cell lines, demonstrating its clinical potential on an experimental level." (PMID 39582530, 2024). "As for the joint expression of ERCC6/ ERCC8, double positivity was related to small tumor size (P = 0.005), Borrmman I-II stage (P < 0.001), TNM I-II stage (P = 0.001) (P < 0.001 for T stage), Lauren intestinal type (P = 0.014) of GC and negative perineural invasion (P = 0.015)." (PMID 34316408, 2021). "Six of nine lncRNAs (MIR1.1HG, LOH12CR2, LOC100506405, ERCC8.AS1, LINC00520, and LINC00567) were differentially expressed between tumor tissues and normal tissues in TCGA datasets." (PMID 36438557, 2022). "Furthermore, we have validated the oncologic function of ERCC8 in LUAD and implied its potential as a novel target for this highly heterogeneous tumor with chemotherapy resistance." (PMID 39582530, 2024). "When adjusting for certain parameters in the Cox multivariate analysis, analyses results of ERCC6 and ERCC8 expression with IHC and RNA-seq data no longer maintained independent predictive power, which may be due to the complexity of tumor progression." (PMID 34316408, 2021).
ERCC8 also shares sentences with these, for which no sentence is quoted: genetic disease (3 papers); anhidrosis (1); breast tumors (1); cerebral palsy (1); congenital myasthenia (1); developmental delay (1); endometrioid carcinoma (1); growth failure (1); hepatic (1); hereditary neurodegenerative disorder (1); insulin-dependent diabetes (1); Intellectual disability (1); Leukoencephalopathy (1); lung carcinoma (1); melanoma (1); metabolic disorders (1); neurodevelopmental disorder (1); neurological diseases (1); ovarian carcinoma (1); peripheral T-cell lymphoma (1); Serous carcinoma (1); Werner syndrome (1); xeroderma pigmentosum (1).